WNT3A (Wnt family member 3A)
Diseases named in the same sentence as WNT3A in open-access papers (continued):
Sharing a sentence is not in itself a finding about the gene and the disease.
ischemia (9 papers, 2012 to 2025). A hypoperfusion of the BLOOD through an organ or tissue caused by a PATHOLOGIC CONSTRICTION or obstruction of its BLOOD VESSELS, or an absence of BLOOD CIRCULATION. "Researchers have found that the intranasal delivery of recombinant Wnt3a successfully activates the Wnt/β-catenin pathway, rescuing the ischemia-induced reduction of endogenous Wnt3a." (PMID 41304786, 2025). "Further experiments revealed a significant decrease in Cys-C expression in the Sen + Ischemia + Wnt3a group compared with either of the other two ischemia groups, but it still presented with a higher level compared with the untreated Ctrl group." (PMID 35936906, 2022). "The Sen + Ischemia + Wnt3a group showed significantly improved myocardial morphology with a high level of microthrombi, indicating that the tissue microcirculation was severely damaged after myocardial infarction." (PMID 35936906, 2022). "The Sen + Ischemia + Wnt3a group demonstrated approximately 20% infarct size due to ischemic injury with significantly decreased lesion area than that in the Sen + Ischemia group (p < 0.05)." (PMID 35936906, 2022). "In ischemia/reperfusion injury, ExoCXCR4 promoted the proliferation and tube formation of microvascular endothelial cells and play an antiapoptotic role via the Wnt-3a/β-catenin pathway." (PMID 33381162, 2020). "Accordingly, antagonizing Wnt3a/Wnt5a binding to its receptors FZDs prevents heart failure upon ischemia." (PMID 29564334, 2018). "Accordingly, intra-myocardial injection of Wnt3a post-ischemia reduces CPC differentiation into cardiomyocytes." (PMID 29564334, 2018). "The present study was a proof of concept study to evaluate Wnt3a treatment using the endothelin-1 focal ischemia model." (PMID 22815838, 2012). "However, the Sen + Ischemia + Wnt3a group showed significantly improved cardiac function compared with Sen + Ischemia group (p < 0.05)." (PMID 35936906, 2022). "In ischemia/reperfusion injury, ExoCXCR4 can promote the proliferation and tube formation of microvascular endothelial cells and play an antiapoptotic role via the Wnt-3a/β-catenin pathway." (PMID 33381162, 2020). "To study the behavior of Wnt3a over-expression in an ischemic environment, we used the endothelin-1 ischemia model Endothelin-1 is a potent vasoconstrictor that has been used to induce ischemic injury resembling a thrombo-embolic stroke event when injected directly into rodent brain." (PMID 22815838, 2012). "However, the Sen + Ischemia + Wnt3a group showed a significant decrease in the apoptotic rate of cardiomyocytes approximately 40%, compared with either of the other two ischemia groups (p < 0.05), but it still presented with a higher level relative to both Ctrl and Sen groups." (PMID 35936906, 2022). "However, the Sen + Ischemia + Wnt3a group showed a significant decrease in LDH, cTnT, and CK-MB levels compared with the Sen + Ischemia group (p < 0.05), but it still presented with higher levels of these biomarkers relative to the Ctrl group." (PMID 35936906, 2022).
pancreatic cancer (9 papers, 2015 to 2025). "Nearly all the pancreatic cancer cell lines except Bxpc3 showed increased Wnt3a protein compared to normal pancreatic duct cells." (PMID 37031249, 2023). "To evaluate the involvement of GPC1 in Wnt signaling in pancreatic cancer cells, we determined the expression of Wnt3a." (PMID 37031249, 2023). "Another example is the molecules miR-15a and miR-16-1, whose dysregulation allows prostate and pancreatic cancers to develop by influencing the signaling pathways associated with CCND1 (cyclin D1), WNT3A and BCL2." (PMID 35269947, 2022). "WNT3a was able to reverse docosahexaenoic acid-induced growth inhibition in human pancreatic cancer PANC-1 cells." (PMID 27391060, 2016). "Wnt3a is considered a major initiating factor in the Wnt/β-catenin canonical pathway and Wnt7a has been shown to be highly expressed in pancreatic cancer cell lines." (PMID 25669977, 2015). "We show that PG545, by directly interacting with Wnt3a and Wnt7a, inhibits Wnt/β-catenin signaling leading to inhibition of proliferation in pancreatic tumor cell lines." (PMID 25669977, 2015). "Riluzole inhibited the expression of β-catenin, Wnt3a, Wnt5a, WSP, TCF and LEF in both MIA PaCa-2 and AsPC-1 pancreatic cancer cells." (PMID 35773307, 2022). "Se deficiency increases Wnt expression levels in cardiac tissue; in contrast, Wnt3a expression was observed to reverse DHA-induced growth inhibition and apoptosis in human pancreatic cancer cells." (PMID 33805447, 2021). "PG545 interacts with Wnt3a and Wnt7a to preventing them from binding to their receptors, LRP5/6 and Frizzled, resulting in significantly decreased β-catenin levels, suppressed tumor growth and metastasis in pancreatic tumors." (PMID 25669977, 2015).
Cerebral ischemia (8 papers, 2009 to 2026). Restriction of arterial blood supply to the brain associated with insufficient oxygenation to support the metabolic requirements of the tissue. "After cerebral ischemia, Wnt3a, as an important signal transduction activator in Wnt signaling pathway, can activate the downstream key factor β-catenin." (PMID 39976471, 2025). "It has been shown that after cerebral ischemia, Wnt3a mainly enhances the expression levels of β-catenin and TCF-4 and the downstream activation of the transcription factors Pax6 and Neurogenin2 in SD rats." (PMID 37242489, 2023). "This neuroprotective response is mediated by increase of Wnt3a and inhibition of Dkk1 elevation, triggered after cerebral ischemia." (PMID 19360103, 2009). "After inducing focal cerebral ischemia in mice using a local injection of a lentivirus expressing Wnt3a-HA into the striatum or SVZ region, a dramatic increase in the number of differentiated BrdU-positive cells in the striatum into mature and immature neurons in the SVZ was observed." (PMID 37242489, 2023). "Interestingly, hypoxic post-conditioning (HPC) increased the levels of nuclear β-catenin and the expression of Wnt3a, while decreasing the expression of Dkk1 after cerebral ischemia in rats." (PMID 33071819, 2020). "In the present study, cerebral ischemia resulted in downregulation of the Wnt-3a and β-catenin proteins, while LMP2 inhibition rescued Wnt-3a and β-catenin protein expression in the LMP2-shRNA group compared with the control-shRNA group (P < 0.001)." (PMID 34857032, 2021). "In our model of focal brain ischemia, Wnt3a did not rescue the neurons in the ischemic environment, although it was overexpressed in the ischemic striatum." (PMID 22815838, 2012).
liver cancer (8 papers, 2015 to 2025). An epithelial or non-epithelial malignant neoplasm that arises from the liver. "Variant 3 of Collagen XVIII suppresses Wnt3a-induced stabilization of β-catenin and then down-regulates cyclin D1 and c-Myc to reduce tumor cell growth in colorectal and liver cancer cell lines." (PMID 26369691, 2015). "Additionally, WNT3a antagonized the growth inhibition of liver cancer stem cells induced by 8-bromo-7-methoxychrysin." (PMID 27391060, 2016). "In other diseases, particularly liver cancer, NRF2 and the WNT pathway exhibit interplay, where WNT3A stimulates NRF2, and NRF2 either stabilizes β-CATENIN or promotes its transcription to activate the WNT pathway." (PMID 40494896, 2025). "With regard to liver cancers, it was shown that SNHG9 promoted hepatoblastoma tumorigenesis via miR-23a-5p/Wnt3a axis." (PMID 35887228, 2022).
non-small cell lung carcinoma (8 papers, 2012 to 2026). A group of at least three distinct histological types of lung cancer, including non-small cell squamous cell carcinoma, adenocarcinoma, and large cell carcinoma. "TOP2A plays an important role in regulating immunotherapy and VM formation in non-small cell lung cancer by regulating the expression of the classical WNT ligand Wnt3a and the immune checkpoint PD-L1." (PMID 37407689, 2023). "Therefore, we believe that Wnt3a is an excellent antitumor target and future work should also consider Wnt3a as a potential marker for VM channels in non-small cell lung cancer." (PMID 37407689, 2023). "Of importance is that, through GSK-3β interaction, Prune_1 was found to activate β-catenin signaling cascade and to further promote Wnt3a secretion in non-small cell lung cancer (NSCLC) cells; thus, a connectome related to the WNT signaling activation was identified." (PMID 34745995, 2021). "Endogenous Wnt3a and LRP6 levels were assessed in seven non-small cell lung cancer cell lines (A549, H322, H596, H460, H358, H2009, and H1299) by western blot analysis." (PMID 22606268, 2012). "Finally, the 5-HTR3A receptor has also been reported to facilitate the development and progression of both colorectal and non-small-cell lung cancer through NLRP3 and Wnt3A/β-catenin signaling, respectively, thus confirming its role in carcinogenesis." (PMID 39766077, 2024). "Further correlation analysis of Wnt3a and VM expression in clinical specimens by immunohistochemistry revealed that 56 of 141 non-small cell lung cancer specimens expressed VM, while 32 of 56 VM-positive specimens had Wnt3a expression, while none of 78 Wnt3a-negative specimens expressed VM." (PMID 37407689, 2023).
esophageal squamous cell carcinoma (7 papers, 2012 to 2025). Esophageal squamous cell carcinoma (ESCC) is a type of esophageal carcinoma (EC) that can affect any part of the esophagus, but is usually located in the upper or middle third. "For example, Wnt3a expression is reported to be significantly associated with poor prognosis of numerous cancers, including esophageal squamous cell carcinoma and HCC." (PMID 30814912, 2019). "It was found that RNF168 and WNT3A mRNA levels were negatively correlated with the survival rate (overall survival and disease-specific survival) of patients with esophageal squamous cell carcinoma." (PMID 33493132, 2021). "STAT3 expression was upregulated by the Wnt3a, Wnt5a and Wnt6 ligands in cultured mouse embryonic stem cells, and by constitutively activate β-catenin in esophageal squamous cell carcinoma." (PMID 23056515, 2012). "Recent study discovered that FASN/PA-mediated Wnt3A (Cys77) palmitoylation promotes Wnt3A membrane localization and the translocation of β-catenin into the nucleus, further activating Wnt3A/β-catenin pathway and promoting the formation of EMT phenotype in esophageal squamous cell carcinoma." (PMID 40681504, 2025).
lung adenocarcinoma (7 papers, 2016 to 2021). A carcinoma that arises from the lung and is characterized by the presence of malignant glandular epithelial cells. "GPC5 was recently reported to be an epigenetically silenced tumour suppressor in lung adenocarcinoma, where it binds Wnt3a at the cell surface to inhibit Wnt/β-catenin signalling." (PMID 29089486, 2017). "PITX2 could activate the Wnt/β-catenin signaling pathway via upregulating Wnt family member 3A (WNT3A), thereby promoting the development of lung adenocarcinoma." (PMID 34372865, 2021). "Furthermore, PITX2 could also promote the development of lung adenocarcinoma via enhancing the expression of WNT3A and activating the Wnt/β-catenin pathway." (PMID 34372865, 2021). "In the H1703 human lung adenocarcinoma cell line, knockdown of PTPRK enhanced Wnt3a induced signaling in Topflash reporter assays as well as expression of the endogenous Wnt target gene AXIN2." (PMID 31934854, 2020).
myeloma (7 papers, 2009 to 2023). "It has been reported that overexpression of Wnt3A in bone has a marked inhibitory effect on myeloma‐induced osteolytic bone lesions." (PMID 37840014, 2023). "DKK1 blocks Wnt3a-induced β-catenin accumulation in multiple myeloma and Wnt3a-mediated B lymphopoiesis of CD133+CD10− hematopoietic progenitor cells and CD10+ B progenitor cells." (PMID 26369691, 2015). "Further studies are required to address whether Wnt3A is also involved in osteoblastic change in other cancer than myeloma." (PMID 37840014, 2023). "Wnt3a-induced OPG expression could be diminished in osteoblasts co-cultured with a DKK1-expressing multiple myeloma (MM) cell line or primary MM cells." (PMID 26369691, 2015). "Likewise, treatment with recombinant Wnt3a stimulates bone formation and attenuates multiple myeloma cell growth in myelomatous severe combined immunodeficiency (SCID)-hu mice." (PMID 26369691, 2015). "One is that bones engrafted with Wnt3a-expressing multiple myeloma H929 cells are preserved; the other is that treatment of myelomatous SCID mice carrying the primary disease with recombinant Wnt3a stimulates bone formation and attenuates multiple myeloma growth." (PMID 25499541, 2014).
cleft lip (6 papers, 2018 to 2024). Congenital defect in the upper lip where the maxillary prominence fails to merge with the merged medial nasal prominences. "WNT3A gene dysfunction has been previously associated with the formation of cleft lip and palate in humans." (PMID 37366674, 2023). "Wnt3a regulates palate morphogenesis, and mutations in this gene cause cleft lip and palate in humans and mice." (PMID 30459452, 2018). "The rs3121310 polymorphism is a variation localized in the intronic region of WNT3A gene and associated with male patients affected by non-syndromic cleft lip palate." (PMID 39329917, 2024). "The results of our study show that the decreased number of WNT3A immunoreactive cells in all evaluated cleft-affected tissue groups compared to controls again emphasizes the role of WNT signaling during non-syndromic cleft lip and palate morphogenesis in human postnatal tissue." (PMID 37366674, 2023). "Fgf18 and Wnt3a were associated with non-syndromic cleft lip with or without palate (NSCL/P)." (PMID 36685938, 2022). "The aim of this study was to detect and compare the immunohistochemical expression of cleft candidate gene coded proteins (DLX4, MSX2, HOXB3, SHH, PAX7, SOX3, WNT3A, and FOXE1) in the non-syndromic unilateral cleft lip patient tissue and control group tissue." (PMID 33917041, 2021).
Obesity (6 papers, 2016 to 2025). Accumulation of substantial excess body fat. "When using palmitic acid (PA) to simulate high-fat-induced in vitro obesity state, the expression levels of WNT3a and β-catenin were significantly decreased in the PA group compared with those in the control group." (PMID 41278194, 2025). "In the current experiment, the results showed that in HF treatments the expressions of Wnt3a and β-catenin in the liver were significantly decreased which verified the function of the Wnt3a/β-catenin pathway in obesity." (PMID 35990272, 2022). "In the present study, skeletal muscle IGF‐1, Wnt3a, Wnt5a and Wnt7a mRNAs were all reduced in subjects with obesity." (PMID 35293040, 2022). "It would be interesting to investigate whether Wnt3a-induced insulin production from the specific neurons in the hypothalamus can regulate the food intake and protect from obesity." (PMID 26956881, 2016). "miR-103 also promotes apoptosis in preadipocytes by targeting WNT family member 3a (Wnt3a), suggesting that miR-103 could be related to increased adipocyte apoptosis found in the WAT of subjects with obesity." (PMID 38786092, 2024).
pulmonary fibrosis (6 papers, 2020 to 2025). Chronic progressive interstitial lung disorder characterized by the replacement of the lung tissue by connective tissue, leading to progressive dyspnea, respiratory failure, or right heart failure. "Betulinic acid acted in this way in a pulmonary fibrosis model by reducing Wnt3a- or LiCl-induced transcriptional activity in a luciferase assay or at the level of several Wnt target genes in NIH-3T3 fibroblasts." (PMID 40427472, 2025). "It has been showed that Wnt3a was significantly upregulated in experimental and human idiopathic pulmonary fibrosis." (PMID 33390951, 2020). "Besides, the Wnt3a/β-catenin signaling pathway was significantly activated in PQ induced pulmonary fibrosis." (PMID 33390951, 2020). "In the present study, we found that the expressions of Wnt3a, β-catenin, WISP1 were increased in the mouse model of PQ-induced pulmonary fibrosis, and ATG administration suppressed the activation of Wnt signaling." (PMID 33390951, 2020). "Experimental data showed that nintedanib attenuated Wnt3a-induced ColIa1, Fn, and α-SMA expression in vitro, suggesting that nintedanib treatment rebalanced the accumulation of Wnt3a-induced ECM components, which is crucial for the amelioration of pulmonary fibrosis." (PMID 32231574, 2020).
Stroke (6 papers, 2012 to 2025). Sudden impairment of blood flow to a part of the brain due to occlusion or rupture of an artery to the brain. "Following a stroke, a decrease in endogenous Wnt3a and β-catenin was observed in the subventricular zone, a key neurogenic region." (PMID 41304786, 2025).
type 2 diabetes mellitus (6 papers, 2021 to 2024). A type of diabetes mellitus that is characterized by insulin resistance or desensitization and increased blood glucose levels. "In type 2 diabetes mellitus (T2DM) mice, inhibiting the Wnt3a/β-catenin pathway recently reduced bone formation, leading to osteoporosis." (PMID 39371752, 2024).
Alzheimer disease (5 papers, 2019 to 2024). A progressive, neurodegenerative disease characterized by loss of function and death of nerve cells in several areas of the brain leading to loss of cognitive function such as memory and language. "These categories include WNT (WNT1, WNT3A, WNT6, AXIN2, TNF2, MMP7), Alzheimer disease presenilin (WNT1, WNT3A, WNT6, MMP7), cadherin (WNT1, WNT3A, WNT6) and Notch (LFNG, HES1) signaling pathways." (PMID 38928376, 2024).
hepatoblastoma (5 papers, 2021 to 2025). Hepatoblastoma (HB) is a malignant hepatic tumor and is the most common pediatric liver cancer. "For instance, SNHG9 promotes carcinogenesis in hepatoblastoma by downregulating miR-23a-5p and upregulating Wnt3a." (PMID 36741904, 2022). "Eventually, we elucidate that SNHG9 promotes hepatoblastoma tumorigenesis via the miR-23a-5p/WNt3a axis." (PMID 34539877, 2021). "All these findings provide strong evidence that SNHG9 promotes hepatoblastoma tumorigenesis via downregulating miR-23a-5p and upregulation Wnt3a." (PMID 34539877, 2021). "Wnt3a mRNA expression was found to be significantly upregulated in hepatoblastoma primary tissue and cell lines." (PMID 34539877, 2021). "Next, we determined the relative expression of Wnt3a in hepatoblastoma primary tissue and cell lines." (PMID 34539877, 2021). "SNHG9 promotes hepatoblastoma tumorigenesis through wnt3a/miR-23a-5p axis." (PMID 34539877, 2021). "As a result, further research has to be carried out to understand the underlying uncovered molecular mechanisms of WNT signaling and Wnt3a in the aggressive development of hepatoblastoma tumors and to identify new therapeutic targets genes for the treatment of HB patients." (PMID 34539877, 2021). "Hence, SNHG9/miR-23a-5p/wnt3a might be a novel and promising therapeutic target for hepatoblastoma patients." (PMID 34539877, 2021).
leukemia (5 papers, 2012 to 2022). A malignant (clonal) hematologic disorder, involving hematopoietic stem cells and characterized by the presence of primitive or atypical myeloid or lymphoid cells in the bone marrow and the blood. "Both Fzd1 and its ligand Wnt3a are important members of the Wnt/Frizzled signaling pathway, decreased expression of which have been implicated in aberrant inflammatory processes and leukemia development." (PMID 33378745, 2020). "It has been observed that increased expression of some WNT ligands such as WNT3a, induces activation of the canonical pathway, accompanied by an increase in the proliferation and survival of leukemia cells." (PMID 22313908, 2012). "Furthermore, cordycepin abolished the effect of Wnt3a-induced β-catenin in leukemia cells." (PMID 24086728, 2013).